RN7SL715P (RNA, 7SL, cytoplasmic 715, pseudogene)
Gene: Miscellaneous RNA gene on chromosome 3 (155,437,538 to 155,437,823, reverse strand). Ensembl gene ENSG00000272096.
Homologues: Orthologues: chimpanzee Metazoa_SRP (99% identical), macaque Metazoa_SRP (93% identical). Paralogues in human: RN7SL1 (81% identical), RN7SL2 (81% identical), RN7SL3 (80% identical), RN7SL45P (79% identical), RN7SL577P (78% identical), RN7SL597P (78% identical), RN7SL186P (78% identical), RN7SL187P (78% identical), RN7SL220P (78% identical), RN7SL126P (77% identical), RN7SL30P (77% identical), RN7SL336P (77% identical), and 707 more.